PPARG (peroxisome proliferator activated receptor gamma)
Diseases named in the same sentence as PPARG in open-access papers (continued):
Sharing a sentence is not in itself a finding about the gene and the disease.
Obesity (continued). "In addition, curcumin exerts an influence on metabolism through the activation of PPARγ to ameliorate obesity/insulin resistance related disorders and certain inflammatory diseases." (PMID 36092543, 2022). "Since the maintenance of a healthy metabolic state depends on the correct adipogenesis in the SAT, an increase in the miR-19 family expression levels in obesity could contribute to the pathology of obesity, mediated by a decrease in the expression of PPARγ." (PMID 36555437, 2022). "In addition, ABA improves insulin sensitivity and obesity‐related inflammation through a mechanism requiring immune cell PPARγ." (PMID 36355391, 2022). "Previous studies indicate an important role for PPARG in diseases, such as obesity and diabetes." (PMID 35207731, 2022). "Moreover, a study reported that green tea polyphenols prevent HFD-induced obesity by increasing adiponectin levels, and alleviation of PPARγ phosphorylation." (PMID 36505461, 2022). "In sum, our present work identifies three molecules, (i) the obesogenic factor ACBP, (ii) the ACBP receptor GABAAR, and (iii) the ACBP-transactivating TF PPARγ, as elements of a vicious amplification loop that likely contributes to the pathogenesis of obesity and its comorbidities." (PMID 35436993, 2022). "We hypothesize that BFE could help ameliorate obesity more significantly than FE by regulating the expression of PPARγ, C/EBPα, and adiponectin." (PMID 36364945, 2022). "PPARγ, a nuclear receptor that acts as a ligand-inducible transcription factor that regulates fat storage and glucose homeostasis, exerting antioxidant and antiinflammatory effects, is downregulated by diet-induced obesity." (PMID 35223953, 2022). "Moreover, the expression of miR-34a has also been reported to be negatively associated with peroxisome proliferator activated receptor γ PPARγ expression in visceral WAT of patients with obesity." (PMID 36010657, 2022). "(-)-Epigallocatechin-3-gallate (EGCG), a green tea catechin, exhibited PPARα and PPARγ agonist properties in subcutaneous adipose tissues, but PPARγ antagonist activity in epididymal adipose tissue to reduce obesity and epididymal white adipose tissue weight in HFD mice via activation of AMPK." (PMID 36092543, 2022). "Together, these results suggest that OHT administration may be an effective treatment for obesity, helping weight loss either through a direct action on CB1 or through an alternative pathway involving PPARγ that results in CB1 inhibition." (PMID 35276827, 2022). "The lack of PPARγ activity is associated with a variety of diseases, such as diabetes, obesity, and high blood pressure." (PMID 34983495, 2022). "As transcription factors have been found to play an increasingly important regulatory role in the development and expansion of adipose tissue, many transcription factors such as C/EBPα, C/EBPβ, and PPARγ have been regarded as potential targets for obesity-related metabolic diseases." (PMID 35883405, 2022). "This might explain miscellaneous results obtained by various authors which prove a lack of association between genetic SNPs of multiple genes, including PPARG and obesity." (PMID 36466447, 2022). "The obesity-related gene phosphatase and tensin homolog was a direct target of miR-216a, which regulates expression of adiponectin receptor 1, caveolin-1, caveolin-2, and PPARγ." (PMID 35711801, 2022). "Moreover, the induction of adiponectin by means of the PPARγ agonism suppresses the elevation in CCL2 levels by blocking TNF- α signaling, thereby attenuating obesity-associated PPAT inflammation." (PMID 35406450, 2022). "Since both betulinic acid and Gleevec antagonizing PPARγ were effective in both diabetes and obesity, exploring novel PPARγ antagonists could be a promising approach for the treatment of diabesity." (PMID 35563411, 2022). "Furthermore, we found that the protective alleles against obesity (MC4R rs17782313 T and PPARG rs1801282 C) were associated with weight loss effectiveness." (PMID 35292917, 2022).
Obesity (continued). "In addition, the effects of chebulinic acid on other adipogenesis-related pathways, including antagonistic effects on PPARγ, are required to further clarify mechanisms of anti-obesity effects of chebulinic acid." (PMID 35055051, 2022). "This study provides an alternative strategy for the modification of PPARγ target gene expression through phase separation, which may alter the course of obesity and insulin resistance that involve PPARγ signaling." (PMID 35473936, 2022). "In addition, ginsenoside Rc can resist obesity by inhibiting the expression of PPARγ and CCAAT/enhancer binding protein (C/EBP)." (PMID 35647185, 2022). "In obesity, PPARG regulates adipocyte maturation and differentiation." (PMID 35207731, 2022). "In our geographical area, research on PPARG and obesity has been limited so far to two studies." (PMID 36466447, 2022). "Therefore, a new approach has been proposed in the treatment and prevention of obesity and diabetes—repressing the PPARγ activity by using its antagonists." (PMID 35885378, 2022). "Adipogenesis through PPARγ activation supports healthy adipose tissue remodeling in obesity." (PMID 36065376, 2022). "PPARγ function is supported by the adipokine adiponectin, that is found in higher concentrations in individuals with a lean bodyweight compared to those with obesity." (PMID 35844529, 2022). "In agreement with in vitro observations, in vivo prenatal BPS exposure was shown to result in white adipose tissue hypertrophy and the up-regulation of PPARγ gene expression in HFD-fed mice, being indicative of the role of BPS in increasing susceptibility to dietary obesity." (PMID 35202251, 2022). "MiR-27a may play a critical role in the pathophysiology of obesity-induced insulin resistance in mice by regulating macrophage polarization via inhibiting PPARγ." (PMID 35978298, 2022). "Peroxisome proliferator-activated receptor gamma (PPARγ) agonists improve adipogenesis and insulin resistance, as well as dyslipidemia, without reducing food intake, and mutations in the PPARγ are associated with obesity-related phenotypes." (PMID 35387194, 2022). "Recent research has established that apigenin is a PPAR modulator that inhibits obesity-induced metabolic syndrome via suppressing PPARγ and PPARα, resulting in activation/inhibition of upstream or downstream targets, such as STAT3, C/EBP-α, SREBP-1c, CD36, and Nrf2 in adipose tissues." (PMID 36092543, 2022). "Those with obesity have been reported to have greater glucose-lowering with thiazolidinediones, which act to improve insulin sensitivity and lipid metabolism by stimulating the nuclear receptor peroxisome proliferator-activated receptor gamma (PPARG)." (PMID 36699039, 2022). "Similarly, it has been shown that SAB moderated lipid disorders by suppressing PPARγ-mediated adipogenesis in mice with high-fat diet-induced obesity." (PMID 35528835, 2022). "PPARγ was directly associated with obesity, meanwhile the lack of correlation found between the leptin-related gene and obesity was mainly due to distinct dietary habits across populations." (PMID 36551995, 2022). "PPARγ also regulates several metabolic diseases such as obesity and diabetes." (PMID 36088760, 2022). "Blocking the SUMOylation of PPARγ at Lys107 in mice can achieve enhanced insulin sensitivity without causing excessive obesity." (PMID 36551260, 2022). "Similarly, PPARγ is a regulator of adipocyte production and differentiation, related to the pathology of many diseases, including obesity, diabetes, atherosclerosis, and cancer, and is also widely described as having anti-osteogenic effects." (PMID 35769158, 2022). "In addition, previous studies have shown that AO increased the level of PPARγ in white tissues to improve obesity and insulin resistance, suggesting the potential activities of AO targeting PPAR family proteins." (PMID 35087411, 2021).
Obesity (continued). "Therefore, VS extract effectively diminished obesity and hyperglycemia by suppressing C/EBPα-mediated lipogenesis in the AT and liver, enhancing PPARα-mediated fatty acid β-oxidation in muscle, and PPARγ-mediated insulin sensitivity in AT and muscle." (PMID 33671428, 2021). "Therefore, PPARγ appears as a likely common element shared by metabolically unhealthy obesity and placental development disorders." (PMID 34884974, 2021). "Therefore, the ratio of mature caspase-1 and the level of PPARγ can be represented as an “NLRP3-accelerating index” in obesity." (PMID 33500734, 2021). "In conclusion, L‐14 extract from Lactobacillus significantly inhibits the differentiation of mouse 3T3‐L1 cells and hBM‐MSCs to mature adipocytes via AMPK and PPARγ signalling pathways and alleviates systemic inflammation and obesity in vivo in an HFD mouse model." (PMID 33830560, 2021). "Under pathological states, such as high glucose and obesity, the activation of PPARγ in pancreatic β-cells might aggravates apoptosis and affect glucose homeostasis." (PMID 34335468, 2021). "Among them, it highlights (MAP2K5 and PPARG) with a negative effect on the endothelial cell migration, for which SNPs have been repeatedly associated with obesity in several populations (especially in Asians)." (PMID 33803198, 2021). "Several in vitro studies have demonstrated that resveratrol has an anti-obesity effect by negatively regulating white adipogenesis via inhibiting PPARγ and C/EBPα, activating Sirtuin 1 (SIRT1) and (PPARγ Coactivator 1) PGC1α, attenuating white adipogenesis and lipid accumulation." (PMID 34371900, 2021). "Furthermore, their anti-obesity effect is carried out by inhibiting the transcriptional activities of PPARγ, suppressing adipocyte differentiation, proliferation, and lipogenesis, and promoting adipocyte apoptosis, lipolysis, and fatty acid oxidation." (PMID 34371900, 2021). "This suggests that B. thetaiotaomicron may contribute to reducing obesity in infants by protecting AT against inflammatory cytokines by activating PPARγ expression." (PMID 34835958, 2021). "Further research showed that the constitutively deacetylated PPARγ (K268R/K293R) mutant mice resisted HFD-induced obesity by increasing brown remodeling in WAT, and they maintained the insulin-sensitizing response to TZD while displaying few adverse effects on fat deposition." (PMID 34445679, 2021). "It was reported that circTshz2-2 increases adipogenesis-related gene expression, such as Pparγ and Fabp4, in obesity while other reports suggest that Tshz2 regulates tumorigenesis and epigenetic methylation in breast and prostate cancers, and is involved in the development of zebrafish." (PMID 34561612, 2021). "Altogether, the protective effects of rhein against obesity could appear to rely on the regulation of ERs, autophagy, and inflammation, possibly also by PPARγ and INSR." (PMID 34516329, 2021). "For example, miR-27a, which plays a critical for obesity by regulating insulin resistance in adipocytes, seems to facilitate the crosstalk between adipocytes and skeletal muscle, inducing insulin resistance by PPARG." (PMID 34107965, 2021). "PPARγ antagonists have been reported to suppress HFD diet-induced obesity." (PMID 33494317, 2021). "PPARG, ADAMTS5, TIMP4, ANXA1, AGTR1, and CXCL12 genes are evidently associated with obesity, suggesting that the influence of these genes on obesity may be similar to the influence of fat accumulation in hMSCs." (PMID 34899844, 2021). "PPARγ and C/EBPα act as crucial interactive regulators that mediate organismic metabolism diseases that comprise several aspects of pathologic diseases such as obesity, cancer, and inflammation." (PMID 35221861, 2021). "The inhibition of PPARγ expression in hypertrophic adipocytes has been observed during obesity, which may explain the decrease in mitochondrial gene expression, including that of March5." (PMID 34445679, 2021).
Obesity (continued). "Furthermore, a report demonstrated that the activator of PPARA, PPARD, and PPARG is of great anti-obesity therapeutics due to the regulation of fat and gluconeogenesis." (PMID 34889899, 2021). "Recent studies have shown that in KDM2A knockout in macrophages, the level of H3K36me2 at the PPARγ locus is significantly enhanced, making macrophages inclined to M2 polarization, thus preventing mice from obesity and insulin resistance induced by a high-fat diet." (PMID 34575926, 2021). "Specifically, Brd4 cooperates with PPARγ in ATMs to regulate the expression of Gdf3, which acts on the adipocytes to suppress the expression of lipases and lipolysis, resulting in fat accumulation and the development of obesity." (PMID 33830083, 2021). "However, the association between rs1801282 in PPARγ and psoriasis, and low level of PPARγ expression were reported in Egyptian patients with obesity and metabolic syndrome." (PMID 34445309, 2021). "Because nutrient overload is a major cause of increased levels of metabolic DAMPs and low-grade inflammation in obesity 49, we hypothesized that PPARγ could be a key factor in attenuating nutrient overload-induced inflammation." (PMID 33500734, 2021). "Lactobacillus was proved to inhibit HFD-induced obesity by down-regulating PPARγ and C/EBPα." (PMID 33776618, 2021). "Brd4 might cooperate with distinct transcription factors, such as NF-κB and PPARγ, to differentially regulate the expression of genes in ATMs to modulate the development of obesity and insulin resistance." (PMID 33830083, 2021). "A better understanding of PPARγ 5′ UTRs may provide clues for controlling obesity, type 2 diabetes, and insulin resistance." (PMID 32184808, 2020). "Interestingly, in old female GWAT, the mRNA levels of Pparγ and Pgc1α were upregulated with obesity but downregulated with ADRB3 stimulation." (PMID 31983693, 2020). "Furthermore, Rg3 modulates obesity through peroxisome proliferator-activated receptor gamma (PPARγ) regulation, by suppressing signal transducer and activator of transcription 5 (STAT5) phosphorylation." (PMID 32161549, 2020). "PPARγ is involved in resistin expression, which is strictly related to obesity and type 2 diabetes." (PMID 32463311, 2020). "EIA10 inhibited PPARγ signaling as well as the development and progression of obesity." (PMID 33198343, 2020). "It is hypothesized that Se may have anti-obesity effects through modulation of PPARγ signaling and development of lipophilic Se compounds capable of binding PPARγ is of particular interest." (PMID 32344656, 2020). "A significant increase in hepatic PPARγ is one of the common phenotypes of steatotic animals associated with obesity and without obesity, which lack TAG-storing capacity in adipocytes." (PMID 32192216, 2020). "Besides possessing antioxidant activities, ASX was found to have antagonistic effects on adipocytes and agonistic effects on peritoneal macrophages, acting as a selective PPARγ modulator, related to obesity." (PMID 32260306, 2020). "This speculation can be supported by several reports showing interactions between PPARγ and factors such as sex, physical activity level, dietary fat intake, total energy intake, and breast-feeding practices on obesity phenotypes." (PMID 32384785, 2020). "Given that IAAs exhibit both anti-obesity and anti-diabetic effects via activation of PPARα and PPARγ, IAAs were hypothesized to markedly prevent obesity-induced cognitive decline." (PMID 31940997, 2020). "Increased expression of PPARγ was found in multiple tissues in diet-induced obesity models (DIO)." (PMID 32158560, 2020). "Phosphorylation of PPARγ at Ser273 is essential for insulin resistance related to obesity." (PMID 32821266, 2020). "In addition, macrophage-specific deletion of PPARγ impairs M2 polarization and predisposes HFD-fed mice to develop obesity and insulin resistance." (PMID 33260769, 2020). "PPARγ has been identified as a target for obesity treatment." (PMID 33322300, 2020).
Obesity (continued). "Therefore, PPARγ has been a primary pharmacological target for drug discovery for the treatment of obesity and T2D." (PMID 32973516, 2020). "Moreover, PPARγ is directly related to obesity in rodents, resulting in the overexpression of PPARγ in adipose tissue." (PMID 32463311, 2020). "According to reports, LBP can reduce PPARγ activity to relieve obesity." (PMID 33447177, 2020). "In particular, PPARα and PPARβ/δ play a central role in the oxidation of fatty acids, as well as in the improvement of lipid and cholesterol profiles, which reduces adiposity and prevents the development of obesity, while PPARγ contributes to energy storage by enhancing adipogenesis." (PMID 32630591, 2020). "This study adds details to the mechanisms of obesity induced by PPARγ phosphorylation." (PMID 33329381, 2020). "PETIC may have a protective effect on obesity and atherosclerosis by regulating the expression of PPARγ, LXRα, ABCA1, SR-A1, CD36, and NF-κB." (PMID 33261070, 2020). "Taken the rosiglitazone-induced metabolic improvement and gene expression restoration together, our results suggest that increasing PPARγ transcriptional activity could overcome the HFD-induced obesity and adipocyte hypertrophy in PPARγ3RA/+ mice." (PMID 32973516, 2020). "Given the importance of PPARγ in adipose development, obesity and related diseases, in the future we will use CRISPR-Cas9 technology to explore the in vivo importance and underlying molecular mechanism of PPARγ1 uORF in physiological and pathological conditions." (PMID 32184808, 2020). "Overall, it is suggested that MiR-27a in WAT might represent an important target in macrophage activation and regulate local or systematic obesity-induced insulin resistance via PPARG/nuclear factor kappa B (NFKB)." (PMID 33207733, 2020). "Similarly, dysregulation of gene expression upon phosphorylation of PPARγ on S273 by cyclin-dependent kinase 5 (CDK5) is particularly apparent in the context of obesity." (PMID 32249683, 2020). "As CRC is associated with obesity and Waist-to-Hip Ratio (WHR), the peroxisome proliferator-activated receptor gamma (PPARG), PPARG co-activator 1 (PPARGC1) family (e.g., PPARGC1A and PPARGC1B) may be strong candidate genes predisposing to CRC." (PMID 30838172, 2019). "Additionally, miRNAs can control the process of adipogenesis during obesity, including transcriptional and post-transcriptional factors such as peroxisome proliferator-activated receptor gamma (PPARγ) and CCAAT/enhancer binding proteins alpha (C/EBPα)." (PMID 31817583, 2019). "For THY1 membrane glycoprotein (10-fold upregulated in our study), it was shown that overexpression decreases the activity of PPARγ and blocks adipocyte formation and it could therefore become a therapeutic target in obesity." (PMID 31083566, 2019). "Thus, PPARγ signaling in the brain influence the energy balance and stimulate the obesity phenotype." (PMID 31683535, 2019). "In addition, PPARγ activation in Tregs promotes their accumulation in visceral adipose tissue and protection from obesity-induced insulin resistance." (PMID 31683535, 2019). "A smaller share is attributed to genetic factors, which include the polymorphism of following genes: fat mass and obesity-associated gene (FTO), commonly referred to as the “obesity gene”, and gene coding for peroxisome proliferator-activated receptor gamma (PPARγ), resistin, and adiponectin." (PMID 31737129, 2019). "Future studies should determine if PPARγ is a suitable candidate for pharmacological intervention to treat both obesity and childhood low bone density which may influence the incidence of SCFE and Blount’s disease." (PMID 31798753, 2019). "A recent study suggested that hepatocyte SHP1 might affect peroxisome proliferator–activated receptor gamma- (PPARγ-) mediated hepatic inflammation by presenting obesity-induced NAFLD." (PMID 31236111, 2019).